ANXA1 (annexin A1)
Diseases named in the same sentence as ANXA1 in open-access papers (continued):
Sharing a sentence is not in itself a finding about the gene and the disease.
cervical carcinoma (13 papers, 2008 to 2025). A carcinoma arising from either the exocervical squamous epithelium or the endocervical glandular epithelium. "Here, we examined the effect of the N‐terminal peptide Ac2‐26 of ANXA1 on the HaCaT cell line (normal) and HeLa cell line (cervical cancer) co‐cultured with endothelium cell‐conditioned medium (HMC)." (PMID 30984541, 2019). "Evidence indicates that ANXA1 that is phosphorylated at the tyrosine 21 residue (ANXA1-TYR) is present in higher levels in cervical cancer than in normal tissues." (PMID 24782913, 2014). "Upregulation of annexin A2 (in line with our results) and A5 has been described in cervical carcinoma; however, annexin A1 was downregulated suggesting different roles for these annexins in the carcinogenesis of cervical squamous cell carcinoma." (PMID 19367286, 2009). "We have shown through liquid chromatography that annexin A1 is present in the serum of patients with invasive cervical cancer and certain precancerous specimens." (PMID 18637184, 2008). "Phosphorylated annexin A1 was up regulated in diseased states in comparison to control and its level was strongly detected in the serum of cervical cancer patients compared to controls." (PMID 18637184, 2008). "The expression of ANXA1 is downregulated during cervical carcinogenesis, and its expression varies in different clinical stages, degrees of tissue differentiation, and lymph node status of cervical cancer." (PMID 41497316, 2025). "This adds to the suggestion that the ANXA1 protein may have an anti‐proliferative role in the cervical cancer cells through the MAPK family pathway, as observed after the peptide treatment and stimulation with HMC." (PMID 30984541, 2019). "This pathway may be affected by the up-regulation of phosphorylated annexin A1 and may play a role in the carcinogenesis of cervical cancer through increase cellular proliferation." (PMID 18637184, 2008). "Based on our observation, annexin A1 could potentially serve as a target to image, monitor and treat cervical cancer, particularly in advance or recurrent cases where therapeutic options are presently limited." (PMID 18637184, 2008). "The link between annexin A1 and cervical cancer may have clinical significance." (PMID 18637184, 2008). "While this expression is not specific to cervical cancer, in a patient with no other underlying pathology annexin A1 expression in the serum maybe used as a marker for disease progression, recurrence or to monitor response to therapy." (PMID 18637184, 2008). "Some of the most promising cervicovaginal fluid-based biomarkers for cervical cancer found until now are ACTN4, VTN, ANXA1, ANXA2, CAP1, and MUC5B." (PMID 35645371, 2022). "Complementary to this was the observation that by chromatographic separation using the Beckman PF2D Proteome Lab annexin A1 was strongly expressed in the sera of cervical cancer patients and was absent in sera of a cohort of unexposed aging nuns." (PMID 18637184, 2008).
colon carcinoma (13 papers, 2014 to 2025). "In this study, we found that ANXA1 can also be used as a diagnostic and prognostic indicator in colon cancer." (PMID 36678567, 2023). "We have previously reported that high expression of ANXA1 protein in gastric and colon cancer is associated with worse prognosis." (PMID 31461932, 2019). "Taken together, in both colon cancer and RC, high ANXA1 expression is associated with therapy resistance and apoptosis inhibition, while its suppression promotes cell death by reducing the anti-apoptotic markers, i.e., Bcl-2, and by increasing pro-apoptotic proteins, i.e., Bax." (PMID 41283264, 2025). "In conclusion, we demonstrated that overexpression of ANXA1 in patients and cell lines of colon cancer cause cell hyperproliferation and poor prognosis, and ANXA1 is the key factor in weakening the autophagic death induced by honokiol via stabilizing mtROS in colon cancer." (PMID 36678567, 2023). "Similarly, strong ANXA1 expression may be considered a prognostic marker in colon cancer, given its significant association with tumor growth and metastasis." (PMID 41283264, 2025). "Considering its functional roles, ANXA1 contributes to chemoresistance, mainly to 5-fluorouracil (5-FU), a fundamental chemotherapeutic agent used in the management of both RC and colon cancers." (PMID 41283264, 2025). "Here, we demonstrated that annexin A1 (ANXA1) was overexpressed in tumors of 50% of colon cancer patients, and ANXA1 overexpression was significantly negatively correlated with the poor prognosis of colon cancer." (PMID 36678567, 2023). "To further investigate the role of ANXA1 protein in colon cancer growth in vivo, we constructed tumor-bearing nude mice models by subcutaneous injection of the HCT116-shControl cells and the HCT116-shANXA1 cells in BALB/c mice." (PMID 36678567, 2023). "The heterogeneity is also reflected by the ANXA1 expression difference in seven colon cancer cell lines." (PMID 36678567, 2023). "Chemoresistance is a major bottleneck in colon cancer treatment, and ANXA1 is thought to regulate chemoresistance in a variety of tumors." (PMID 36678567, 2023). "To explore the pathological significance of ANXA1 in colon cancer, we successively recruited 50 colon cancer patients, of which 25 patients (50%) showed positive expression of ANXA1 for their tumors via immunohistochemistry." (PMID 36678567, 2023). "ANXA1 promoted the abnormal proliferation of colon cancer cells in vitro and in vivo by regulating the cell cycle, while the knockdown of ANXA1 almost totally inhibited the growth of colon cancer cells in vivo." (PMID 36678567, 2023). "Until now, the function of ANXA1 in colon cancer, especially the relationship between ANXA1 expression and its response to drug treatment, has hardly been reported." (PMID 36678567, 2023). "To investigate the effect of ANXA1 on colon cancer cell function, we first detected the expression levels of ANXA1 in seven colon cancer cell lines." (PMID 36678567, 2023). "In the beginning, we searched the database and found that the mRNA expression of ANXA1 was elevated markedly in colon tumors compared to adjacent tissues or non-tumoral mucosa, suggesting the potential role of ANXA1 in the pathogenesis of colon cancer." (PMID 36678567, 2023). "Here, we found annexin A1 overexpressed in colon cancer cell lines compared with cancer cells of other origin and over-represented in human primary colorectal lesions as well as hepatic metastases compared with their adjacent healthy tissue counterparts." (PMID 31545917, 2019). "Similar to ANXA1, also CALD1 has been shown to display opposite roles in cancer and invasion, since its expression has been associated to reduced cell invasion in colon cancer cell lines." (PMID 26657294, 2016). "For example, in gastric and colon carcinomas ANXA1 has a pro-invasive role through its interaction with FPRs." (PMID 25510623, 2014).
colon carcinoma (continued). "Moreover, while ANXA1 is markedly upregulated in 5-FU-resistant colon cancer cells, its suppression has been shown to restore the drug sensitivity." (PMID 41283264, 2025). "For example, Annexin A1 shows increased levels of GlcNAcylation in colon cancer patients." (PMID 38612832, 2024). "In colon cancer, ANXA1 was considered a possible druggable target." (PMID 39194522, 2024). "Thus, our study highlights ANXA1 as a promising target to develop novel therapeutic drugs to treat colon cancer, even to reverse chemotherapy resistance of colon cancer." (PMID 36678567, 2023). "Next, we found that ANXA1 regulates the cycle distribution of colon cancer cells." (PMID 36678567, 2023). "Based on these results, we speculated that ANXA1 might be a druggable target to control colon cancer and overcome drug resistance." (PMID 36678567, 2023). "Furthermore, ANXA1 antagonized the autophagic death of honokiol in colon cancer cells via stabilizing mitochondrial reactive oxygen species." (PMID 36678567, 2023). "Here, we uncovered that ANXA1 promotes colon cancer cell proliferation by regulating the cell cycle, and targeting ANXA1 can enhance the anti-tumor role of honokiol by regulating the autophagic signaling pathway through mitochondrial reactive oxygen species (mtROS)." (PMID 36678567, 2023). "In human colon cancer cells, annexin A1 inhibited NF-κB by directly binding to its p65 subunit." (PMID 31545917, 2019). "Here, we show that annexin A1 was markedly upregulated in colon cancer cell lines compared with cancer cells of other origin and also over-represented in human primary colorectal lesions, as well as hepatic metastases, compared with their adjacent healthy tissue counterparts." (PMID 31545917, 2019). "We found that with the use of immunoblotting, annexin A1 was expressed by multiple cancer cell lines, with more prominent band intensity observed for colon cancer cell lines (MC38, HT-29, HCT116, LoVo) compared with pancreatic (Pan02) or lung (LLC) cancer cells." (PMID 31545917, 2019). "Furthermore, HSP90b and Annexin A1 proteins were found to be GlcNAcylated in colon cancer tissues." (PMID 38612832, 2024). "In this context, ANXA1 facilitates EGFR activation and stabilization, supporting the development of new therapeutic targets in colon cancer and RC." (PMID 41283264, 2025). "Bioactive NH2-terminal peptides of annexin A1 inhibited NF-κB and the growth of SW480 colon cancer cell xenografts in nude mice." (PMID 31545917, 2019). "But ANXA1 can significantly regulate the proliferation ability of both HCT116 cells with higher ANXA1 expression and SW620 cells with lower ANXA1 expression, suggesting that ANXA1 may be a universal target for colon cancer." (PMID 36678567, 2023). "Emerging evidence suggests that ANXA1 may contribute to immune suppression within TME via its functional interaction with the EGFR pathway, a key regulator of cell proliferation and tumor progression in both colon cancer and RC." (PMID 41283264, 2025).
Alzheimer disease (12 papers, 2013 to 2026). A progressive, neurodegenerative disease characterized by loss of function and death of nerve cells in several areas of the brain leading to loss of cognitive function such as memory and language. "Our results underline the potential benefit of ANXA1 in reducing blood–brain barrier leakage, as a promising treatment of Alzheimer’s disease." (PMID 34148071, 2021). "ANXA1 is associated with anti-inflammatory protective actions against toxic mediators such as reactive oxygen species and pro-inflammatory cytokines that exacerbate neuroinflammation in Alzheimer’s disease and other neurodegenerative diseases." (PMID 34148071, 2021). "In this study, we administered human recombinant ANXA1 (hrANXA1) to young 5xFAD mice, a widely accepted model of Alzheimer’s disease, resulting in the reversal of cerebrovascular disruption and the reduction in amyloid-β pathology and memory loss at an early stage of Alzheimer’s disease." (PMID 34148071, 2021). "ANXA1 further appeared as a protective agent in Alzheimer’s disease by affecting amyloid-β clearance, following our recent report that ANXA1 reduced amyloid-β levels in vitro by increasing both microglial uptake and its enzymatic degradation in neurons." (PMID 34148071, 2021). "In the adult brain, changes in ANXA1 expression are associated with neurodegenerative diseases related to BBB dysfunction, such as Alzheimer’s disease, Parkinson’s disease and multiple sclerosis." (PMID 30682787, 2019). "Annexin A1 is elevated in Alzheimer's disease, perhaps as an attempt to repair the faulty blood-brain barrier." (PMID 29359063, 2017). "Anxa1, a central player in anti-inflammatory and neuroprotective role of microglia was identified to be more strongly expressed in Alzheimer’s disease." (PMID 23536833, 2013). "Additionally, ANXA1 levels have been observed to be higher in the brains of individuals with Alzheimer’s disease (AD) as well as in animal models during the initial stages of the disease." (PMID 38961424, 2024). "However, aided by deep sequencing data, various SNPs were identified, suggesting a potential involvement of AnxA1 in Alzheimer’s disease, and revealed roles for AnxA2 in sickle cell disease, but also cardiovascular risk due to elevated LDL cholesterol." (PMID 33810523, 2021). "Therefore, we hypothesized that ANXA1 could be of therapeutic use in Alzheimer’s disease by regulating blood–brain barrier leakage, reducing microvascular damage and amyloid-β pathology." (PMID 34148071, 2021). "The importance of ANXA1 in BBB integrity is supported by its neuroprotective capacities in the periphery of the brain and in neurological diseases, including Alzheimer’s disease (AD)." (PMID 36983004, 2023). "Annexin 1 (ANXA1) is sparingly expressed in microglia of normally aged human brains, with a higher level of expression in Alzheimer’s disease." (PMID 34072307, 2021).
autoimmune disease (12 papers, 2009 to 2023). A disorder resulting from loss of function or tissue destruction of an organ or multiple organs, arising from humoral or cellular immune responses of the individual to their own tissue constituents. "More recently, the role of Annexin A1, in the context of its cell death/survival function, has been reported in nephropathy associated with the autoimmune disease of glomerulonephritis with polyangiitis (GPA)." (PMID 34943928, 2021). "In humans, ANXA1 deficiency can be associated with the autoimmune disease, uveitis." (PMID 29614751, 2018). "The potential role of Annexin A1 in relation to pathogenesis of the autoimmune disease of lupus nephritis (LN) has been investigated using renal biopsy and blood samples of patients afflicted with the disease." (PMID 34943928, 2021). "These in vitro results indicate that annexin A1 prevents the development of a cytokine milieu known to contribute to Th1-mediated autoimmune disorders." (PMID 23638088, 2013). "Because ANXA1 is the main effector molecule of glucocorticoids, glucocorticoids may induce the production of large amounts of ANXA1, which, in most autoimmune diseases, inhibits inflammation." (PMID 37735492, 2023). "Other studies have shown ANXA1 to be anti‐inflammatory in murine models of autoimmune disease." (PMID 35146757, 2022). "We have seen evidence for a role for ANXA1 in mediating T‐cell pathology in autoimmune disease, so could this protein be involved in manipulating Th17 activity?" (PMID 35146757, 2022). "Our results demonstrate that the early exposure of annexin A1 constitutes a molecular mechanism by which apoptotic cells gain their immunosuppressive phenotype to induce peripheral tolerance and prevent the development of autoimmune diseases." (PMID 23638088, 2013). "Together these findings suggest that AnxA1 acts as a positive modulator of T cells and might facilitate the development of autoimmune diseases contributing to aberrant T cell activation." (PMID 19912648, 2009). "The results obtained corroborate the hypothesis that blocking AnxA1 function or expression during autoimmune diseases might open new avenues for the therapeutic control of these pathologies." (PMID 19912648, 2009). "Moreover, ANXA1 deficiency has been linked to the severity of other autoimmune diseases including Uveitis and T1DM and interestingly hrANXA1 treatment can reduce the severity of such autoimmune diseases." (PMID 29614751, 2018). "Although CD is a heterogeneous autoimmune disease, the expression levels of five key genes (TNF, BIRC3, ANXA1, TNIP3, and FKBP11) were significantly higher in most CD tissues than that in normal tissues." (PMID 37047025, 2023).
diabetic nephropathy (12 papers, 2018 to 2024). "The diagnostic model based on FMGs PRKAR2B/ANXA1 has good predictive value for the early and late stages of diabetic nephropathy." (PMID 39498440, 2024). "ANXA1 also been has been shown to be a good diagnostic marker of glomerular injury and in particular diabetic nephropathy." (PMID 31114582, 2019). "Interestingly, tubulointerstitial Annexin A1 expression correlated with ADRP suggestive of its association with lipid abnormalities of diabetic nephropathy patients." (PMID 34943928, 2021). "In chronic diseases, such as diabetic nephropathy, the level of ANXA1 expression in the kidney tissue of patients is significantly increased." (PMID 36658472, 2023). "ANXA1 (as an endogenous mediator) has been demonstrated recently to play an important role in alleviating kidney injury in patients with diabetic nephropathy by resolving inflammation." (PMID 36035163, 2022). "In mice with diabetic nephropathy, ANXA1 ameliorates kidney injuries through facilitating the resolution of inflammation." (PMID 35783659, 2022). "Our previous study found that ANXA1 was upregulated in kidney of patients with diabetic nephropathy and was correlated with renal function and renal outcomes." (PMID 35783659, 2022). "The role of Annexin A1 in diabetic nephropathy has been further investigated in the context of assessment of associated metabolic abnormalities." (PMID 34943928, 2021). "It was concluded that Annexin A1 regulates lipid metabolism (e.g., of PTECs) to ameliorate disease progression, and that its modulation likely offering therapeutic potential for diabetic nephropathy." (PMID 34943928, 2021). "ANXA1 (Ac2-26) is a well-established anti-inflammatory compound that has shown therapeutic potential in a variety of disease models, including lung injury, acute colitis, kidney transplantation and diabetic nephropathy." (PMID 36544058, 2023). "Thus, Annexin A1 may serve as a therapeutic option to ameliorate diabetic nephropathy." (PMID 34943928, 2021). "To gain a better understanding of the role of ANXA1 in the pathophysiology of T2D, we used a murine model of HFD-induced insulin resistance, hepatic steatosis and renal dysfunction (diabetic nephropathy)." (PMID 30972066, 2019).
esophageal cancer (12 papers, 2012 to 2025). A primary or metastatic malignant neoplasm involving the esophagus. "In esophageal cancer, ANXA1 expression was found to be decreased in the cytosol and membrane but overexpressed in the nuclei." (PMID 38893148, 2024). "The miR-196a-5p was initially identified as an oncogenic miRNA which direct targeted annexin A1 to promote proliferation and prevent apoptosis of esophageal cancer cells." (PMID 30621631, 2019). "By contrast, reduced levels of ANXA1 protein expression have been reported in esophageal cancer and laryngeal cancer." (PMID 25490767, 2014). "In esophageal cancer, miR-196a over-expression promotes cell proliferation, anchorage-independent growth and suppresses apoptosis by directly regulating ANXA1." (PMID 22876840, 2012). "Furthermore, we have been intrigued by the lack of detailed information about the correlation of miR-196a and ANXA1 in PC, while the miRNA-mediated mechanism in the reduced expression of ANXA1 in breast, endometrial, and esophageal cancers has been explained." (PMID 29986379, 2018).